TAF15 (TATA-box binding protein associated factor 15)
Description:
RNA and ssDNA-binding protein that may play specific roles during transcription initiation at distinct promoters. Binds to ssRNA containing the consensus sequence 5'-AGGUAA-3'. Can enter the preinitiation complex together with the RNA polymerase II (Pol II).
Synonyms: TAFII68; RBP56; TAF2N; hTAFII68; Npl3
Tractability: PROTAC: UniProt records ubiquitination sites on it; ubiquitination databases record sites on it; its protein half-life has been measured.
Gene: Protein-coding gene on chromosome 17 (35,809,481 to 35,864,615, forward strand). Ensembl gene ENSG00000270647.
Subcellular location: Nucleus; Cytoplasm
Subcellular location (Human Protein Atlas): Nucleoplasm
Pathways (Reactome):
Gene expression (Transcription): RNA Polymerase II Pre-transcription Events; RNA Polymerase II Promoter Escape; RNA Polymerase II Transcription Initiation; RNA Polymerase II Transcription Initiation And Promoter Clearance; RNA Polymerase II Transcription Pre-Initiation And Promoter Opening
Disease: HIV Transcription Initiation; RNA Polymerase II HIV Promoter Escape; Transcription of the HIV genome
Gene Ontology:
Molecular function: protein binding; RNA binding; transcription coregulator activity; mRNA 3'-UTR binding; nucleic acid binding
Biological process: mRNA stabilization; positive regulation of DNA-templated transcription; regulation of DNA-templated transcription
Cellular component: cytoplasm; nucleolus; nucleoplasm; nucleus
Genetic constraint (gnomAD): Loss-of-function variants: 34 observed, 102.81 expected, observed/expected ratio (o/e) 0.33, 90% interval 0.25 to 0.44. The upper end of that interval is the gene's LOEUF score, 0.44, which puts it in group 1 of 6, group 1 being the genes least tolerant of losing a copy. Missense variants: 647 observed, 784.55 expected, observed/expected ratio (o/e) 0.82, 90% interval 0.77 to 0.88. Synonymous variants: 270 observed, 260.37 expected, observed/expected ratio (o/e) 1.04, 90% interval 0.94 to 1.15.
Gene-disease validity (ClinGen):
ClinGen rates the evidence that TAF15 causes each of these diseases.
amyotrophic lateral sclerosis (autosomal dominant): Limited. Amyotrophic lateral sclerosis (ALS) is a neurodegenerative disease characterized by progressive muscular paralysis reflecting degeneration of motor neurons in the primary motor cortex, corticospinal tracts, brainstem and spinal cord.
Homologues: Orthologues: rabbit TAF15 (96% identical), chimpanzee TAF15 (95% identical), pig TAF15 (95% identical), rat Taf15 (91% identical), dog TAF15 (90% identical), mouse Taf15 (89% identical), macaque TAF15 (56% identical), tropical clawed frog taf15 (50% identical), zebrafish taf15 (41% identical), Caenorhabditis elegans fust-1 (24% identical), Drosophila melanogaster caz (23% identical). Paralogues in human: EWSR1 (41% identical), FUS (40% identical).
Diseases named in the same sentence as TAF15 in open-access papers:
TAF15 is named in the same sentence as 55 diseases in open-access papers, as found by Europe PMC text mining. Sharing a sentence is not in itself a finding about the gene and the disease. The quoted sentences say what the papers report.
amyotrophic lateral sclerosis (30 papers, 2012 to 2025). "Here we present evidence that TAF15, which is implicated in the etiology of amyotrophic lateral sclerosis, represents a novel nuclear PKA substrate." (PMID 38568213, 2024). "TATA-binding protein associated factor 15 (TAF15) is involved in the pathology of amyotrophic lateral sclerosis (ALS) and frontotemporal dementia (FTD)." (PMID 36411469, 2022). "The FET protein family includes FUS, EWS and TAF15 proteins, all of which have been linked to amyotrophic lateral sclerosis, a fatal neurodegenerative disease affecting motor neurons." (PMID 27117089, 2016). "Furthermore, point mutations in FUS and TAF15 are associated with neurodegenerative conditions like amyotrophic lateral sclerosis and frontotemporal lobar dementia." (PMID 37961424, 2023). "Since this discovery, several other human RNA-binding proteins with prion-like domains associated with disease were identified including, for instance, FUS, TDP-43 and TAF15 that are linked to amyotrophic lateral sclerosis (ALS) and frontotemporal dementia (FTD)." (PMID 33068411, 2020). "The RNA-binding protein (RBP) TAF15 is implicated in amyotrophic lateral sclerosis (ALS)." (PMID 27378374, 2016). "FET-proteins are also involved in neurological diseases with FUS and TAF15 mutations identified in familial amyotrophic lateral sclerosis (ALS), frontotemporal lobar degeneration (FTLD) and essential tremor disorders." (PMID 26573619, 2015). "Mutations in the FUS, EWS, and the TAF15 genes are reported in familiar and sporadic amyotrophic lateral sclerosis (ALS)." (PMID 23049996, 2012). "FET proteins are relevant in several different cancers and point mutations in either FUS or TAF15, some of which affect their nuclear–cytoplasmic shuttling, can cause neurodegenerative diseases such as amyotrophic lateral sclerosis (ALS) and frontotemporal lobar dementia (FTD)." (PMID 38568213, 2024). "Moreover, it was revealed that PAD4 can competitively inhibit the methylation of some RGG motif proteins including the FET proteins (FUS, EWS and TAF15) and hnRNPA1, and each has been linked to amyotrophic lateral sclerosis (ALS)." (PMID 37778382, 2023). "TAF15 is also a major gene for amyotrophic lateral sclerosis, which is a common neurodegenerative disease." (PMID 37709831, 2023). "Condensates formed by TAF15/hnRNP A1/hnRNP A2 are important drivers of amyotrophic lateral sclerosis." (PMID 36875159, 2023). "FET (FUS-Fused in Sarcoma; EWSR1-Ewings Sarcoma breakpoint region 1; TATA box binding protein Associated Factor 15) proteins have been implicated in neurodegenerative disorders such as Amyotrophic Lateral Sclerosis (ALS) and Fronto-Temporal Lobar Degeneration (FTLD)." (PMID 35440550, 2022). "The second dataset individually depleted three RBPs implicated in amyotrophic lateral sclerosis: FUS, TAF15 and TARDBP." (PMID 31238884, 2019). "Some paraspeckle proteins, such as TDP-13, FUS, EWS, TAF15, HNRNPA1, SS18L1, and SFPQ have been associated with neuro-degenerative diseases, such as amyotrophic lateral sclerosis (ALS) and frontotemporal dementia (FTD)." (PMID 30087896, 2018). "Cabeza (caz) is the single Drosophila melanogaster orthologue of the human FET proteins FUS, TAF15, and EWSR1, which have been implicated in amyotrophic lateral sclerosis (ALS) and frontotemporal dementia." (PMID 30209068, 2018). "Abnormal functions of RNA-binding proteins TAF15, FUS and TDP43 are associated with amyotrophic lateral sclerosis." (PMID 27378374, 2016). "Interestingly, several upregulated DE genes were related to neurodegenerative diseases, such as genes related to Alzheimer’s disease: PSEN2, TREM2, and GAB2; Parkinson’s disease: ATP13A2 and DCTN1; and amyotrophic lateral sclerosis: TAF15 and FUS." (PMID 40877796, 2025).
amyotrophic lateral sclerosis (continued). "In this context, it would be intriguing to note that a number of paraspeckle-enriched RBPs with IDRs, including SFPQ, FUS, EWSR1, TAF15, TDP-43, SS18L1 and HNRNPA1, are mutated in familial cases of amyotrophic lateral sclerosis (ALS) and other neurodegenerative diseases." (PMID 30355755, 2018). "For example, as components of SGs, ATX1, hnRNPA1, TDP-43, TIA1, and TAF15 can lead to the occurrence of neurodegenerative diseases such as Alzheimer’s disease (AD), amyotrophic lateral sclerosis (ALS), and frontotemporal dementia (FTD)." (PMID 37179344, 2023). "Such prion-like proteins have been linked to pathomechanisms of amyotrophic lateral sclerosis (ALS) in humans, in particular TDP43, FUS, TAF15, EWSR1 and hnRNPA2." (PMID 36415860, 2022). "Finally, there was a signature related to neurodegenerative diseases characterized by neuritic plaques and neurofibrillary tangles, specifically through a study of the role of TAF15 in amyotrophic lateral sclerosis (ALS) and the Alzheimer disease-presenilin pathway from PANTHER." (PMID 35235788, 2022). "Moreover, mislocalization of RBPs outside the nucleus such as FUS, TAF15, hnRNP A1, hnRNP A2, and TDP‐43 leads to amyotrophic lateral sclerosis and frontotemporal dementia." (PMID 36875159, 2023). "Genetic analyses of patients with amyotrophic lateral sclerosis (ALS) have revealed a strong association between mutations in genes encoding many RNA-binding proteins (RBPs), including TARDBP, FUS, hnRNPA1, hnRNPA2B1, MATR3, ATXN2, TAF15, TIA-1, and EWSR1, and disease onset/progression." (PMID 32547363, 2020). "Like other proteins of the FET family (FUS, EWSR1 and TAF15; Ewing’s sarcoma (EWS) and TAF15 (TATA-binding protein-associated factor), mutations in fused in sarcoma (FUS) are directly linked with protein aggregation in amyotrophic lateral sclerosis (ALS) and frontotemporal dementia patients." (PMID 31238957, 2019). "One of the experiments under study selected FUS, TAF15 and TARDBP (referred to as TDP43 in the reference), since they are known to be related to amyotrophic lateral sclerosis (ALS)." (PMID 31238884, 2019). "EWS and TAF15 (as well as FUS) can localize to cytoplasmic stress granules and paraspeckles and pathologically accumulate as cytosolic inclusions in patients with amyotrophic lateral sclerosis (ALS) and frontotemporal lobar degeneration (FTLD)." (PMID 36833257, 2023). "Further: The inclusions of FTLD-FUS include other FET proteins (transportin, TAF15 and EWS) and these are not seen in the MND-FUS cases FET proteins TAF15 and EWS are selective markers that distinguish FTLD with FUS pathology from amyotrophic lateral sclerosis with FUS mutations." (PMID 35002606, 2021).
sarcoma (28 papers, 2008 to 2026). A usually aggressive malignant neoplasm of the soft tissue or bone. "Genes encoding the RNA-binding proteins FUS, EWSR1, and TAF15 (FET family proteins) are frequently involved in chromosomal translocations in sarcomas." (PMID 40852926, 2025). "Genes encoding the RNA-binding proteins FUS, EWSR1, and TAF15 (FET proteins) are involved in chromosomal translocations in rare sarcomas." (PMID 40852926, 2025). "ZNF384 fusions to TAF15 and Ewing’s sarcoma gene EWSR1, caused by chromosome translocations have been implicated in acute leukemia." (PMID 24465633, 2014). "FET (FUS, EWSR1, and TAF15) fusion oncoproteins are characteristic for several sarcomas and leukemias, including myxoid liposarcoma and Ewing sarcoma." (PMID 40988026, 2025). "Many sarcomas are driven by fusion proteins, which most commonly include FUsion in malignant lypoSarcoma (FUS), EWS RNA Binding Protein 1 (EWSR1) and TATA-box binding protein Associated Factor 15 (TAF15) as partners." (PMID 37828086, 2025). "FET family proteins comprising FUS, EWSR1, and TAF15 are not only involved in neurodegenerative disease but also act as oncoproteins in sarcoma or leukemia by chromosomal translocation." (PMID 36194562, 2022). "FET fusion oncoproteins containing one of the FET (FUS, EWSR1, TAF15) family proteins juxtaposed to alternative transcription‐factor partners are characteristic of more than 20 types of sarcoma and leukaemia." (PMID 35182012, 2022). "Well-known proteins with LC sequences are the proteins that form the FET family (FUS, fused in sarcoma; EWS, Ewing sarcoma; TAF15, TATA-binding protein-associated factor 2N)." (PMID 33067781, 2021). "For example, all FET RBPs—fused in sarcoma/translocated in liposarcoma (FUS/TLS), Ewing sarcoma breakpoint region 1 (EWS), and TATA-box-binding protein-associated factor 15 (TAF15)—localize into SGs and participate in cancer." (PMID 34095105, 2021). "The EWSR1 gene is a member of the TET (also known as FET) family, including Fused in sarcoma/Translocated in Liposarcoma (FUS/TLS) and TATA-box binding Associated Factor 15 (TAF15)." (PMID 34612781, 2021). "FUS, EWS, and TAF15 are structurally similar multifunctional proteins that were initially discovered in the process of characterization of fusion oncogenes in human sarcomas and leukemias." (PMID 30087896, 2018). "The FET-protein family comprises FUS (fused in sarcoma, and also abbreviated TLS (translocated in liposarcoma)), EWS (Ewing sarcoma breakpoint region 1, and also abbreviated EWSR1) and TAF15 (TATA box binding protein associated factor 68 kDa)." (PMID 26573619, 2015). "FET family proteins consist of fused in sarcoma/translocated in liposarcoma (FUS/TLS), Ewing's sarcoma (EWS), and TATA-binding protein-associated factor 15 (TAF15)." (PMID 24804206, 2014). "FUS, EWS, and TAF15 form the FET family of RNA-binding proteins whose genes are found rearranged with various transcription factor genes predominantly in sarcomas and in rare hematopoietic and epithelial cancers." (PMID 21197473, 2011). "FUS, EWS and TAF15 are structurally similar multifunctional proteins that were first discovered upon characterization of fusion oncogenes in human sarcomas and leukemias." (PMID 18620564, 2008). "The protein EWS1 (Ewing’s sarcoma breakpoint region 1) along with the gene products encoded by FUS (fused in sarcoma)/TLS (translocated in liposarcoma) and the TATA box binding associated factor 15 (Taf15), are RNA and DNA binding proteins that belong to the FET (FUS, EWS, TAF15) family of proteins." (PMID 38653846, 2024). "Together with EWS and TAF15, these FET proteins share structural similarities including the propensity to aggregate, and they all are components of fusion oncogenes associated with sarcomas and leukemias." (PMID 24027631, 2013).
sarcoma (continued). "In addition, the FET protein family, which includes the EWS, TAF15 (TATA-box binding protein associated factor 15), and FUS/TLS (fused in sarcoma/translocated in liposarcoma, herein referred to as FUS) proteins, has been shown to be a part of the splicing machinery." (PMID 33652741, 2021). "TATA-box binding protein associated factor 15 (TAF15) is a member of the FET family of RNA- and DNA-binding proteins which play a role in gene transcription, is a member of the TFIID transcription initiation complex and was shown to undergo translocation in acute leukemias and sarcomas." (PMID 29340097, 2017). "Only two studies investigated the role of Ewing Sarcoma (EWS) and TAF15 and, which along with FUS constitute the FET family." (PMID 41245603, 2025). "TAF15 is a member of FET protein family, which displays a high translocation rate in sarcoma and promotes carcinogenesis." (PMID 37257820, 2023). "Although these sarcomas have variable cell phenotypes, transcriptomes, prevalence, and prognoses, they are all driven by FUS, EWSR1, or TAF15 (sometimes referred to as the ‘FET’ gene family) fused to a transcription factor." (PMID 33669307, 2021). "TAF15, a member of the FET family, has been found rearranged with various transcription factors with cancer promoting functions in sarcomas as well as in rare hematopoietic and epithelial cancers." (PMID 27822437, 2016). "A protein family consisting of translocated in liposarcoma or fusion in sarcoma (TLS/FUS), Ewing’s sarcoma (EWS), and TAF15 is called the TET (TLS/FUS, EWS, TAF15) family and has various roles in gene expression." (PMID 27181033, 2016). "The FET (FUS, EWSR1, and TAF15) fusion oncogenes are characteristic for around 20 different sarcomas and leukemia, including FUS::DDIT3 in myxoid liposarcoma (MLS) and EWSR1::FLI1 in Ewing sarcoma (EWS), the two most common FET sarcoma entities." (PMID 40988026, 2025). "Interestingly, driver fusion genes in sarcomas favor RBPs with LCDs such as EWS/FLI1 and TAF15/NR4A3." (PMID 35954475, 2022). "All cases were characterised by TAF15 filaments, in the absence of filaments of the other FET proteins, fused in sarcoma (FUS) and Ewing's sarcoma (EWS)." (PMID 41648099, 2026).
frontotemporal dementia (18 papers, 2012 to 2026). Frontotemporal dementia (FTD) comprises a group of neurodegenerative disorders, characterized by progressive changes in behavior, executive dysfunction and language impairment, as a result of degeneration of the medial prefrontal and frontoinsular cortices. "For instance, recent evidence has linked EWSR1, another RBP very similar to FUS and TAF15, to frontotemporal lobar degeneration with ubiquitin-positive inclusions (FTLD-U)." (PMID 22919483, 2012). "For example, abundant amyloid filaments of TAF15 were recently found in brain samples from frontotemporal dementia (FTD) patients." (PMID 40196648, 2025). "Cryogenic electron microscopy structures of amyloid filaments extracted from patient brains reveal that the protein TAF15 forms filaments that characterize certain cases of frontotemporal lobar degeneration." (PMID 38057661, 2024). "Potentiated Hsp104 variants also rescue toxicity and aggregation of TAF15 but not EWSR1, two RNA-binding proteins with a prion-like domain that are connected with the development of ALS and frontotemporal dementia." (PMID 25062688, 2014).
Ewing sarcoma (17 papers, 2011 to 2026). A small round cell tumor that lacks morphologic, immunohistochemical, and electron microscopic evidence of neuroectodermal differentiation. "The FET protein family, which includes FUS (Fused in Sarcoma), EWG (Ewing Sarcoma) and TAF15 (TATA binding association factor 15) proteins, is a group of RBPs containing three different long IDRs characterized by the presence of RGG motifs." (PMID 33262375, 2020). "Notably, two of the FUS studies also investigated related proteins belonging to the FET protein family: TATA-binding protein-associated factor 2 N (TAF15) and Ewing’s sarcoma (EWS)." (PMID 41341655, 2025). "The negatively charged pADPr polymers recruits a large spectrum of proteins, including FET (FUS [fused in liposarcoma], EWS [Ewing sarcoma] and TAF15 [TATA binding associated factor 15]) family proteins FUS and TAF15 that rapidly accumulate at DNA lesions induced by micro-irradiation." (PMID 30456359, 2018). "FUS, together with EWS (Ewing's sarcoma) and TAF15 (TBP-associated factor 15) in vertebrates, belongs to the FUS/EWS/TAF15 (FET) or TLS/EWS/TAF15 (TET) family." (PMID 26150427, 2015). "Together with Ewing’s sarcoma (EWS) and RNA polymerase II, TATA box binding protein (TBP)-associated factor, 68 kDa (TAFII68/TAF15), FUS belongs to a family called TET or FET." (PMID 23577159, 2013). "TAF15 belongs to a DNA- and RNA-binding protein family, known as the FET (also named TET) family that comprises TLS/FUS (translocated in liposarcoma), EWSR1 (Ewing sarcoma), and TAF15." (PMID 21647292, 2011). "It is one of Translocated in liposarcoma, Ewing’s sarcoma and TATA-binding protein-associated factor 15 (TET, also named as FET) protein family members that also contains Fused in Sarcoma (FUS) and TATA-box binding protein Associated Factor 15 (TAF15)." (PMID 36230245, 2022). "FUS is highly related to EWSR1, and both are members of the FET (FUS/TLS, EWS, and TAF15) family of RNA binding proteins, while FLI1 and its related genes are members of the ETS family of DNA binding proteins, and together the “FET-ETS” fusions represent nearly all cases of Ewing sarcoma." (PMID 33488267, 2020).
liposarcoma (14 papers, 2011 to 2024). A usually painless malignant tumor that arises from adipose tissue. "Historically, FUS has also been called translated in liposarcoma (TLS) and is a member of the FET family of RNA-binding proteins that include Ewing sarcoma breakpoint region 1 (EWS) and TATA-box binding protein associated factor 15 (TAF15)." (PMID 36263379, 2022).